SOD2 (superoxide dismutase 2)
Diseases named in the same sentence as SOD2 in open-access papers (continued):
Sharing a sentence is not in itself a finding about the gene and the disease.
cardiomyopathy (37 papers, 2011 to 2025). A disease of the heart muscle or myocardium proper. "Surprisingly, mice with knock-in of a SOD2 mutation mimicking constitutive deacetylation of K68 (SOD2K68R) developed cardiomyopathy, revealing the value of adaptive modulation of acetylation at key residues." (PMID 41502422, 2025). "Mice deficient in SOD2 died of cardiomyopathy within 10 days of birth, whereas heterozygous SOD2 (+/−) mice showed ultrastructural damage to the myocardium associated with increased oxidative stress." (PMID 35453408, 2022). "Whilst animal experiments have confirmed that knockout of SOD2 gene in mice can cause fatal cardiomyopathy, the current research data on the role of MnSOD in various human cardiovascular diseases, including AF, are relatively limited." (PMID 36079059, 2022). "On the other hand, deficiency in SOD2 was lethal for mutant mice due to cardiomyopathy." (PMID 38389898, 2024). "Mutations in SOD2 are associated with premature aging and cardiomyopathies." (PMID 37153596, 2023). "In addition, SOD2 mutations are associated with cardiomyopathy, sporadic motor neuron defects, and cancer." (PMID 35821802, 2022). "Mice deficient in SOD2 die of cardiomyopathy within 10 days of birth, whereas heterozygous SOD2(+/–) mice show ultrastructural damage of the myocardium and mitochondria, associated with an increased oxidative stress as well as an activation of apoptotic signaling pathways in the heart." (PMID 34136546, 2021). "Heterozygous (SOD2+/-) knockout mice have a 50% reduction in SOD2 activity with increased mitochondrial oxidative damage, leading to reduced myocardial antioxidant defenses, and causing enlarged/dilated hearts and severe cardiomyopathy." (PMID 28700033, 2017). "Experiments in a cardiomyocyte-specific SOD2 deficient mouse strain revealed that deficiency of SOD2 results in increased ROS levels and subsequent overproduction of electrophilic aldehydes, which serve as mediators of mitochondrial dysfunction and boost cardiomyopathy." (PMID 35821802, 2022). "SOD2 knock-out mice display increased apoptosis and urine acidity, cardiomyopathy and die after birth." (PMID 40904733, 2025). "Decreased peripheral blood expression of SOD2 is correlated with increased hemolysis and cardiomyopathy in SCD." (PMID 35274104, 2022). "It has been reported that sod2 knockout mice die within 3 weeks of birth due to cardiomyopathy, metabolic acidosis, and neurodegeneration." (PMID 36613936, 2022). "As mentioned, the suppression of the antioxidant marker SOD2 and an increase in oxidative stress play a major role in the treatment of cardiomyopathy induced by aging." (PMID 35956039, 2022). "Systemic homozygous knockout of SOD2 in mice led to pre-weaning lethality accompanied by multiple tissue dysfunctions such as cardiomyopathy, fatty liver, metabolic acidosis, and neurodegeneration." (PMID 33504070, 2021). "In contrast, overexpression of both SOD2 and catalase protects the cell from antiretroviral-induced oxidative stress and cardiomyopathy." (PMID 33504070, 2021). "Mechanistically, we found that the cardiac protection by Zn and BSE from IH-induced cardiomyopathy is associated with significant increases in MT- and Nrf2-mediated antioxidants, including NQO-1, SOD-2, and CAT." (PMID 31934264, 2019). "Co-expression of SOD-2 and PolyQ-72 produced a similar suppression of the PolyQ-72-induced cardiomyopathy." (PMID 24367279, 2013). "To investigate whether EPAS1, BNIP3L, and SOD2 induction is a common feature of cardiomyopathy, we also assessed the levels in additional patient hearts with mutations in PKP2 and phospholamban (PLN), associated with ACM and DCM." (PMID 40034852, 2025). "Another interesting finding is that the acetylation rate of mitochondrial proteins, for example, the acetylation of SOD2, was significantly lower in the myocardium of older male than older female cardiomyopathy patients, suggesting that mitochondrial homeostasis is preserved in older male patients." (PMID 37365150, 2023).
cardiomyopathy (continued). "Furthermore, we investigated the expression of the mitochondrial antioxidant SOD2 in the DOX-induced cardiomyopathy mice model and in H9c2 cells stimulated with DOX." (PMID 37373547, 2023). "Of interest, cardiomyopathy triggered by the ablation of desmin, a major muscle-specific intermediate filament protein, is ameliorated by catalase overexpression but deteriorated by SOD2 overexpression." (PMID 33504070, 2021). "The development of a PrD-like spongiform encephalopathy in SOD2 knock-out mice, treated with antioxidants to delay their death from cardiomyopathy, indicated SOD2 may be a contributing factor to PrD pathogenesis." (PMID 34735539, 2021). "However, in marked contrast to worms, SOD2 or SOD1 knockout in mice develop cardiomyopathy, neurodegeneration, or neuromuscular junction degeneration, respectively, and decreased lifespan, while neither SOD1 nor SOD2 overexpression in mice extends lifespan." (PMID 27114848, 2016). "In mammals, SOD1-deficient mice appear normal at birth but show increasing levels of oxidative stress over time, while SOD2-knockout mice can only live for a short span (10 days) before showing cardiomyopathy, as SOD2 responds to numerous inflammatory and oxidative stimuli." (PMID 25714339, 2015). "In addition, the myocardial antioxidation proteins (Nrf2, HO‐1, SOD1, SOD2), Sirt1 (a regulator of cellular ageing, apoptosis, stress, etc) and pAMPK (a regulator of cellular energy homeostasis) were down‐regulated in mouse hearts with doxorubicin cardiomyopathy." (PMID 32918384, 2020). "Mice lacking SOD2 (Sod2−/−) die shortly after birth from cardiomyopathy and neurodegeneration; whereas Sod2+/− mice are viable until adulthood with no change in lifespan and exhibit elevated markers of oxidative damage and increased sensitivity to oxidative stress." (PMID 23844146, 2013).
Alzheimer disease (36 papers, 2005 to 2026). A progressive, neurodegenerative disease characterized by loss of function and death of nerve cells in several areas of the brain leading to loss of cognitive function such as memory and language. "In transgenic mouse models of Alzheimer’s disease (AD) pathology, the deletion of one allele of SOD2 increased amyloid plaque formation while the deletion of SOD1 increased β-amyloid oligomerization, cognitive impairment, and neuronal dysfunction." (PMID 33117127, 2020). "Conversely, Sod1 loss significantly increases Aβ oligomerization, plaque formation and oxidative damage in a mouse model of Alzheimer’s disease, and conditional knockout of Sod2 in the brain is associated with increased levels of oxidative damage and lethality." (PMID 38755517, 2024). "A higher SOD-2 level was reported in Alzheimer’s disease, which would be considered a compensatory response to attenuate oxidative stress damage." (PMID 36298745, 2022). "Within the hippocampus, both CA1 and CA3 regions are reported to have increased oxidative stress in a mouse model of Alzheimer’s disease (APPNL-G-F mice) or in Sod2+/− mice." (PMID 34515928, 2021). "SOD1 and SOD2 are SOD isoenzymes present inside cells, which have been reported to be associated with Alzheimer's disease." (PMID 34650664, 2021). "In the brains of patients affected with Alzheimer's disease (AD) and Parkinson’s disease (PD), mitochondrial MnSOD superoxide dismutase (SOD2) is one of the major targets of oxidative damage." (PMID 29779015, 2018). "Systemic SOD2 overexpression can ameliorate memory deficits in a transgenic Alzheimer’s disease mouse model." (PMID 29345616, 2018). "In addition, a cross of an Alzheimer’s disease mouse model with a SOD2-overexpressing model resulted in lower superoxide levels and prevented learning and memory issues in the mice." (PMID 40644533, 2025). "Thus, microglial PGD2 production inhibited neurogenesis via suppression of SOD2 and 14-3-3ς expressions, which is in agreement with a study of Alzheimer’s disease mouse model." (PMID 34961526, 2021). "In addition, polymorphisms of genes associated with Parkinson (Parkin—PARK2, parkin coregulated—PACRG and superoxide dismutase 2 -SOD2) and Alzheimer diseases (SOD2) modulate susceptibility to leprosy in independent populations." (PMID 30092084, 2018). "In addition, in an Alzheimer’s Disease model, triheptanoin in the context of a ketogenic diet increased the expression of the mRNA levels of Sirt1, Pparg, Sod1 and Sod2." (PMID 27564703, 2016). "Also mentioned earlier, Mn status is reduced in some Alzheimer’s disease patients, and SOD2 antioxidant function is dependent on this transition metal, thus may be supportive evidence that SOD2 function may be a significant factor in the pathogenesis of Alzheimer’s disease." (PMID 38214013, 2024). "Moreover, it has been shown that increases in SOD2 expression do not always relate to reciprocal increases in SOD2 activity, as has been demonstrated in Alzheimer’s disease." (PMID 29099803, 2017).
type 2 diabetes (36 papers, 2007 to 2025). "A significant association was found between the SOD2 Val16Ala polymorphism and macroalbuminuria in a sample of Mexican type 2 diabetes patients." (PMID 24119114, 2013). "Several studies in type 2 diabetes patients have shown significant associations between the SOD2 gene Val16Ala polymorphism and albuminuria, but this association has not been explored in the Mexican population." (PMID 24119114, 2013). "We evaluated the association between the SOD2 gene Val16Ala polymorphism (rs4880) and macroalbuminuria in a sample of 994 unrelated Mexican type 2 diabetes patients." (PMID 24119114, 2013). "Several studies in type 2 diabetes (T2D) patients of Japanese, Korean and Chinese origin, as well as a meta-analysis, have shown significant associations between the SOD2 gene Val16Ala polymorphism and albuminuria, but this association has not been explored in the Mexican population." (PMID 24119114, 2013). "In the men with type 2 diabetes, the 10‐20‐30 cycling training intervention elevated protein expression of SOD2 and ETC complex II, III, IV, and V, maximal activity of CS, as well as protein expression of Na+/K+ α1, Kir6.2, and MCT1." (PMID 33426802, 2021). "To investigate glomerular oxidative stress after type 2 diabetes induction, we stained against glutathione reductase and SOD2 antibodies." (PMID 29991974, 2018). "Previously, we found, in a rat model of type 2 diabetes, increased acetylation of SOD2 and IDH2 decreased their activity and induced mitochondrial oxidative stress, which in turn decreased the activity of Sirt3 due to a decrease in the mitochondrial NAD+/NADH ratio." (PMID 34439446, 2021). "We have previously reported that mitochondrial oxidative stress is induced by decreased superoxide dismutase 2 (SOD2) and isocitrate dehydrogenase 2 (IDH2) activities associated with a reduced intracellular NAD+/NADH ratio and Sirt3 activity in the kidneys of type 2 diabetic rats." (PMID 32507768, 2020). "The SOD2 c.47C>T polymorphism (Ala16Val, rs4880) has been associated with the risks of CAD and type 2 diabetes mellitus (T2DM)." (PMID 31396447, 2019). "Another study demonstrated that Que can regulate the SIRT3 protein to improve the levels of SOD2 and CAT in type 2 diabetes (T2DM) mice." (PMID 38675511, 2024). "It has been reported that glycyrrhizic acid ameliorates HG-induced low expression and activity of AMPK, Sirt1, and SOD2 in renal tubular cells and improves DKD in a mouse model of type 2 diabetes by suppressing ROS and activating the AMPK/Sirt1 pathway." (PMID 34439446, 2021). "10‐20‐30 training improved exercise capacity while increasing expression of SOD2, ETC complex II, III, IV, and V, maximal activity of CS, as well as expression of Na+/K+ α1, Kir6.2, and MCT1 in the men with type 2 diabetes." (PMID 33426802, 2021). "This study investigated the effects of type 1 diabetes (T1D), type 2 diabetes (T2D), and HT on the expression levels of SIRT1, SIRT3, and manganese superoxide dismutase (SOD2)." (PMID 30736780, 2019). "Correspondingly, the treatment of GLP-1 RAs for one week in rats with type 2 diabetes could reduce NOX3 and SOD2 levels in the retina cells, alleviate autophagy through the GLP-1R-ERK1/2-HDAC6 signaling pathway, and finally improve DR." (PMID 36737746, 2023). "Expression of SOD1 did not change with training in men with type 2 diabetes, whereas SOD2 increased, suggesting a training‐induced enhancement in mitochondrial antioxidant protection." (PMID 33426802, 2021). "That expression of muscle SOD1, that is, the cytosolic isoform of SOD, but not SOD2, that is, the mitochondrial isoform of SOD, was lower in the men with type 2 diabetes may suggest that type 2 diabetes is associated with blunted cytosolic antioxidant protection." (PMID 33426802, 2021).
hepatocellular carcinoma (33 papers, 2007 to 2025). A malignant tumor that arises from hepatocytes. "The Ala16Val polymorphism of the Sod2 gene (rs4880) is a common single nucleotide polymorphism, and the Ala-MnSOD variant is associated with an increase in intracellular iron in patients with alcohol-induced liver cirrhosis and an increased risk of hepatocellular carcinoma." (PMID 22072939, 2011). "It has been reported that excessive mitochondrial Ca2+ influx inhibited NAD+-dependent deacetylase activity of SIRT3, followed by a decrease in SOD2 activity, which contributes to aberrant ROS production and metastasis of hepatocellular carcinoma." (PMID 40166941, 2025). "Fluorescence microscopy and MitoSOX Red staining showed that mitochondrial ROS generation was prominently elevated in SOD2-silenced hepatoma cells." (PMID 37827291, 2023). "Exons 1 and 4 of SOD2 transcripts were back-spliced to develop circSOD2, inducing epigenetic alteration and driving hepatocellular carcinoma progression by activating the JAK2/STAT3 signaling pathway." (PMID 38139387, 2023). "For example, circRNA transcribed from the SOD2 gene plays an important role in hepatocellular carcinoma progression." (PMID 36552527, 2022). "Initial tests were done using hepatocellular carcinoma stained for trichrome, SOD2, and glypican." (PMID 34503228, 2021). "Another study reported that curcumin increased intracellular SOD2 level in human hepatoma cells." (PMID 31662771, 2019). "Genetic silencing of superoxide dismutase 2 augmented the HDGF-induced ROS generation and oncogenic behaviors of hepatoma cells." (PMID 37827291, 2023). "Previous genome-wide RNA-seq studies found that a circular RNA derived from SOD2 gene was highly upregulated in hepatocellular carcinoma (HCC), however, the role of circSOD2 in HCC remains largely unknown." (PMID 33234142, 2020). "Immunoblot analysis showed that rHDGF treatment induced SOD2 upregulation in a dose-dependent manner but did not affect SOD1 protein levels in hepatoma cells." (PMID 37827291, 2023). "To further investigate whether HBV has a direct effect on the expression levels of GPx and SOD2 in cell cultures, we transfected the HBV genome into the human hepatoma cell lines C3A and HuH-7." (PMID 22606292, 2012). "CREPT knockdown in hepatocellular carcinoma (HCC) leads to the diminished expression of NF-kB/NRF2 target genes, such as Sod2 and Fth1, contributing to the release of reactive oxygen species (ROS) accumulation and impaired liver function." (PMID 40723282, 2025). "FOXM1 is known to regulate the expression of important AOS genes including catalase, superoxide dismutase 2 (SOD2) and PRDX3 which we found to be highly overexpressed in multiple cancers (group 6), at the exception of catalase, exclusively overexpressed in hepatocellular carcinoma (group 3)." (PMID 24342878, 2013).
Insulin resistance (32 papers, 2012 to 2025). Increased resistance towards insulin, that is, diminished effectiveness of insulin in reducing blood glucose levels. "Most relevant to this study is that increased mitochondrial ROS is implicated in the pathogenesis of insulin resistance and is reversible in vitro and in mice by small molecule antioxidants, SOD2 overexpression, and mitochondrial uncouplers." (PMID 40639664, 2025). "This, in turn, resulted in insulin resistance by the myocardium, a significant downregulation of the endogenous antioxidant enzymes SOD2 and catalase, and diminished LVEF." (PMID 31752330, 2019). "In order to develop a therapeutic aspect to our findings we decided to deliver SOD2 upregulated cells to reduce inflammation and insulin resistance secondary to inflammation." (PMID 26652025, 2015). "Enhanced production of superoxide anion radical in inguinal white adipose tissue of mice through adipocyte‐specific deletion of mitochondrial SOD2 could potentiate mitochondrial biogenesis, lowering insulin resistance." (PMID 40926357, 2025). "In DN and metabolic disease, genotype-dependent responses linked to ACE I/D, eNOS, and SOD2 polymorphisms complicate drug selection, while non-vasodilating BBs can exacerbate insulin resistance and dyslipidemia." (PMID 41463309, 2025). "However, under conditions of metabolic disruption such as that in T2D, the increase in SOD2 activity can lead to increased hydrogen peroxide accumulation, contributing to oxidative stress and insulin resistance." (PMID 37698290, 2023). "In our study, SOD2 was the only senescence marker induced explicitly by the EGCG-EVs, a fact previously reported for EGCG during an in vivo study and linked to its capacity to prevent the oxidative stress caused by free fatty acid-induced insulin resistance." (PMID 37833751, 2023). "In addition, Rha treatment modulated insulin resistance and increased gene expression of antioxidant enzymes (Cat, Sod2, Gpx3, Mgst1, Prdx3, Gsta4, Gsr, and Sod1) in the ovaries of the PCOS rats." (PMID 35663203, 2022). "In this report, we tested the hypothesis that increased O2 ̇ˉ scavenging capacity by SOD2 overexpression would prevent muscle insulin resistance in HF-fed mice." (PMID 25992608, 2015). "Therefore, we reasoned that ablating NOX4 and abrogating the resultant H2O2-dependent NFE2L2 antioxidant defense response, and, in particular, reducing SOD2, would promote mitochondrial oxidative stress to diminish insulin signaling and promote insulin resistance." (PMID 38060313, 2023). "Indeed, the heterozygous deletion of Sod2 and consequent increased mitochondrial O2•– promote insulin resistance in chow-fed mice, whereas SOD2 overexpression, or the expression of mitochondria-targeted catalase attenuate systemic insulin resistance in HFD-fed mice." (PMID 38060313, 2023). "The current report demonstrates that SOD2 overexpression does not alleviate muscle insulin resistance even when combined with increased scavenging of its reaction product, H2O2." (PMID 25992608, 2015).